IL18 (interleukin 18)
Diseases named in the same sentence as IL18 in open-access papers (continued):
Sharing a sentence is not in itself a finding about the gene and the disease.
coronary artery disease (52 papers, 2007 to 2025). "Clinically, higher serum IL-18 levels are associated with the occurrence of congestive heart failure, coronary artery disease, and myocardial ischemia, and IL-18 is found in symptomatic (unstable) atherosclerotic plaques." (PMID 37551283, 2022). "A prospective study and an updated meta-analysis found that circulating IL-18 levels are positively associated with coronary heart disease incidence." (PMID 31427887, 2019). "An earlier study reported that IL-18 levels are a strong independent factor of death from cardiovascular causes in patients with coronary artery disease." (PMID 31427887, 2019). "Recently, a meta-analysis of the association of IL-18 with coronary heart disease identified circulating IL-18 as a possible risk factor of cardiovascular disease." (PMID 30717382, 2019). "A recent large meta-analysis assessed the association between coronary heart disease risk and several other pro-inflammatory cytokines, including IL-18, matrix metalloproteinase-9, soluble CD40 ligand and tumour necrosis factor-α (TNF-α)." (PMID 28477314, 2017). "The present study investigated the presence and influence of IL-18 genetic variants on gene- and protein expression in stable coronary artery disease (CAD) patients." (PMID 22141572, 2011). "In patients with known coronary artery disease, circulating IL-18 levels as well as polymorphisms in the IL-18 gene were associated with future cardiovascular mortality." (PMID 20331890, 2010). "Drp1-associated mitochondrial fission has been shown to promote the formation of inflammatory vesicles and pro-inflammatory factors (e.g., cysteine-3 and IL-18), accelerating the progression of ischemic heart disease." (PMID 39737905, 2024). "Reports on circulating IL‐18's predictiveness for cardiovascular mortality and endpoints in coronary disease and ACS clash." (PMID 38402570, 2024). "Several proinflammatory cytokines, such as IL-6, IL-18, TNF-α and C-reactive protein, have been reported to be independently associated with the risk of coronary heart disease." (PMID 37308900, 2023). "High serum levels of IL-18 have recently been identified as a strong predictor of death in patients with coronary artery disease and acute ischemic stroke." (PMID 35204237, 2022). "In a prospective study of 1229 patients with coronary artery disease, at the 4-year follow-up, serum IL-18 levels were significantly higher in patients with fatal cardiovascular events than in those who did not die." (PMID 30717382, 2019). "In another study, IL-18 levels were measured in serum samples from 130 coronary artery disease (CAD) patients." (PMID 31024619, 2019). "Positive associations were described for IL-18 and TNF-α only, with relative risks of coronary heart disease per 1-SD higher levels of 1.13 (95% CI 1.05–1.20) and 1.17 (1.09–1.25), respectively." (PMID 28477314, 2017). "It would be of interest to determine if the effect of statins on IL-12 and IL-18 levels are a class effect of the drugs, and if statin treatment of subjects with the inflammatory stimulus of coronary artery disease results in increased IL-12 and IL-18 release." (PMID 25699211, 2015). "Increased levels of circulating IL-18 have proved to be a strong and independent predictor of cardiovascular death in patients with coronary artery disease (CAD)." (PMID 24599060, 2014). "RA patients had significantly higher levels of IL-1β, IL-6, and IL-18 compared to controls.Disease activity (DAS-28) and RF positivity were major risk factors for ischemic heart disease in RA.Better disease control and remission can reduce cardiac complications in RA patients." (PMID 41179568, 2025). "Finally, it is also worth noting that after IL-1β blockade with canakinumab in patients with ischemic heart disease, in the CANTOS trial, IL-18 remained as the main proinflammatory factor associated with increased CV risk." (PMID 35160217, 2022).
coronary artery disease (continued). "Furthermore, IL-18 genetic variations have been reported to influence the serum levels of IL-18 and the clinical outcomes of patients with coronary artery disease." (PMID 32487168, 2020). "In prospective studies, IL-18 is a strong independent predictor of coronary artery disease." (PMID 31354731, 2019). "In addition, variation within the IL-18 gene is known to influence the circulating concentrations of IL-18 and clinical outcome in patients with coronary heart disease." (PMID 23741523, 2013). "Thus, a meta-analysis showed that high levels of IL-6, IL-18, and TNFα increase the risk of non-fatal myocardial infarction or coronary heart disease death." (PMID 39741876, 2024). "This study was aimed to investigate the prognostic significance of the IL-18+183 A/G polymorphism (rs5744292), single and in coexistence with the matrix metalloproteinase (MMP)-9 -1562 C/T (rs3918242) polymorphism, in patients with stable coronary artery disease (CAD)." (PMID 24040261, 2013). "Thus, serum IL-18 level has been recently identified as a strong independent predictor of death from cardiovascular causes in patients with coronary artery disease regardless of the clinical status at admission." (PMID 19690642, 2007). "Although data on the role of IL-18 in predicting coronary events are contradictory, many studies have shown its utility as a strong independent predictor of death from CV causes in patients with coronary artery disease regardless of the clinical status at admission." (PMID 35204237, 2022). "In coronary artery disease, statins especially atorvastatin, can reduce expression of the NLRP3 inflammasome as well as downstream factors IL-1β and IL-18." (PMID 31354731, 2019). "In the blood samples draw from patients with coronary artery disease, the peripheral blood mononuclear cells express higher levels of NLRP3 inflammasome and the inflammasome‐dependent IL‐1β and IL‐18 cytokines when compared with the control patients." (PMID 28470940, 2017). "Genotype distribution, Allelic frequencies, Chi square, Odds ratio and 95% confidence interval (CI) of IL-18 –137G>C in controls, CAD patients and FDRS are presented in and it was found that homozygous GG is significantly associated with occurrence of coronary artery disease." (PMID 25822970, 2015). "In addition, IL-18 is closely related to myocardial IRI and poor prognosis of patients with ischemic heart disease." (PMID 40564918, 2025). "Although baseline IL‐18 levels were slightly higher in individuals with incident coronary heart disease compared to noncases, this difference lacked clinical significance." (PMID 38402570, 2024). "In patients with PsA and in the subgroup with PsA+ ischemic heart disease (IHD), IL-18 positively correlated with atherogenic index (AI) (rho = 0.46 and rho = 0.67, respectively) and TG serum concentrations (rho = 0.4 and rho = 0.675), while negatively with HDL levels (rho = −0.37 and rho = −0.608)." (PMID 35160217, 2022). "CSF3, IL-1A, CCR7, IL-18, and MAPK14, as well as IL-17 signaling pathway and cytokine and cytokine receptor interaction signaling pathway related with inflammatory response might be the potential biomarker and targets for the treatment of coronary artery disease." (PMID 33777109, 2021). "Choi's study examined IL‐18 levels within 2 weeks following an ACS episode, whereas Tiret's research involved individuals with coronary heart disease, not exclusively ACS cases." (PMID 38402570, 2024).
gout (52 papers, 2012 to 2025). A condition characterized by painful swelling of the joints, which is caused by deposition of urate crystals. "In a previous study, cytokines such as interleukin (IL)-16 and IL-18, which are common mediators of inflammation, exhibited strong associations with the severity of gout." (PMID 40364122, 2025). "IL-18 is reported to be elevated in patients with gout, associated with serum urate levels and postulated to contribute to the development of cardiovascular comorbidities." (PMID 37810213, 2023). "However, both IL-1β and IL-18 play an important role in the context of CV risk and therefore the activation of the inflammasome in gout opens up new scenarios worthy of discussion." (PMID 40710524, 2025). "However, IL-18, one of the main proinflammatory cytokines related to the pathogenesis of gout, was significantly associated with the CXCR4 level." (PMID 36979628, 2023). "To explore the role of TLRs and key cytokines in gout pathogenesis, we reanalyzed a publicly available dataset, focusing on the expression of TLRs, IL-1β, IL-18, TNF-α, IL-10, and TGF-β in patients experiencing gout flare versus remission." (PMID 41583461, 2025). "This activation induces the release of pro-inflammatory cytokines, including IL-1β and IL-18, driving the characteristic symptoms of gout attacks." (PMID 40299440, 2025). "This modulation aids in alleviating symptoms linked to MSU-induced gouty arthritis, such as neutrophil infiltration in knee joints, joint circumference and the production of TNF-α, IL-1β, IL-6, and IL-18." (PMID 38094893, 2023). "The serum IL-1β and IL-18 levels in the gout patients were significantly higher than in the controls (7.31 ± 11.84 vs. 0.46 ± 0.91, p = 0.004 and 100.51 ± 47.63 vs. 68.49 ± 32.55, p = 0.002, respectively)." (PMID 36979628, 2023). "MSU can directly stimulate monocytes/macrophages to regulate the release of inflammatory factors such as TNF-α, IL-1β, and IL-18, thereby promoting gout inflammatory response." (PMID 36673346, 2023). "The NOD-like receptor family, pyrin domain containing 3 (NLRP3) inflammasome can be activated by MSU crystals, resulting in the production of its downstream effectors interleukin (IL)-1β and IL-18 in gout patients." (PMID 36814289, 2023). "In the present study, we confirmed that the IL-1β and IL-18 expression was increased by a stimulation with MSU crystals as well as in the blood of gout patients, together with CXCR4 and CXCL12." (PMID 36979628, 2023). "As a clinical drug for gouty arthritis treatment, colchicine (COL) can suppress the activation of caspase-1 and prevent the release of IL-1β and IL-18, thereby inhibiting the occurrence of gouty arthritis." (PMID 36297105, 2022). "Alternatively, IL-1α, IL-1β, and IL-18 drive pathology in a range of human diseases, such as gouty arthritis, autoinflammatory disease, or cytokine storm in systematic infectious diseases." (PMID 36551320, 2022). "At the onset of gouty arthritis, MSU is involved in caspase-1 activation, which causes the production of interleukin-1β (IL-1β) and interleukin-18 (IL-18), inducing proinflammatory responses." (PMID 36297105, 2022). "Mechanistic, genetic, and biomarker studies establish a strong link between pathological inflammasome activation, leading to IL-1β and IL-18 secretion and the progression of RA and gout." (PMID 35629398, 2022). "Serum IL-18, an inflammasome-related cytokine, was reported to be higher in gout patients, and the serum IL-18 level was correlated with the level of C-reactive protein (CRP) and the erythrocyte sedimentation rate (ESR)." (PMID 34830282, 2021). "Loganin inhibited MSU crystals-induced secretion of inflammatory cytokines such as IL-1β and IL-18, resulting in the suppression of gout inflammation in tissues injected with MSU crystals." (PMID 33670601, 2021). "The expression of IL-1β and IL-18 was increased in the peripheral blood mononuclear cells of patients with active gout." (PMID 34830282, 2021).
gout (continued). "Loganin reduced the production of mature IL-1β and IL-18 in macrophages and gout tissues stimulated with MSU crystals." (PMID 33670601, 2021). "Plasma concentrations of IL-1β, IL-18, IL-6, and IL-8 are elevated in the gout patients, but little is known about the role of these cytokines in the progression of gout." (PMID 31803174, 2019). "MSU crystals engage the Nlrp3 inflammasome, leading to the activation of caspase-1 and production of IL-1β and IL-18 within gout-affected joints, promoting the influx of neutrophils and monocytes." (PMID 31803174, 2019). "In the one study of 957 older Italians free of renal disease or gout, having higher uric acid was associated with increased neutrophils, CRP, IL-1ra, IL-6, IL-18 and TNFα." (PMID 28786993, 2017). "Previous studies have identified polymorphisms in the NALP3 inflammasome, TLR-4, CARD8, IL-1β, IL-18, and CD14 genes to be associated with gout." (PMID 29023487, 2017). "Several studies have focused on the relationship between gout and candidate inflammatory genes including IL-1β, IL-6, IL-8, IL-18, and TNF-α, however, the disease pathogenesis is still not fully understood." (PMID 26890073, 2016). "Mechanistically, studies have shown that dysregulation of the signaling cascade is associated with gout, while the circadian clock can regulate the expression and activation of NLRP3, thereby controlling the secretion of IL-1β and IL-18 in various tissues and immune cells, particularly macrophages." (PMID 40495130, 2025). "Given that monosodium urate crystals drive gouty inflammation primarily through NLRP3 inflammasome activation and the subsequent release of IL-1β and IL-18, the suppressive effects of GDF15 on these mediators suggest a potential regulatory role in modulating gout-associated inflammatory responses." (PMID 40722837, 2025). "In patients with osteoarthritis without any clinical signs of gout, researchers found that uric acid levels in the synovial fluid were associated with IL-18, IL-1β, and radiographic severity of OA." (PMID 39775222, 2024). "The release of IL-1β, IL-18 and TNF are tightly associated with the pathogenesis of gout." (PMID 39130631, 2024). "IL-1β and IL-18 are crucial proinflammatory cytokines that play a role in the pathogenesis of gout." (PMID 36979628, 2023). "For example, the most highly cited study published in Nature showed that MSU engaged the caspase-1-activating NALP3 inflammasome, resulting in the production of active interleukin (IL)-1beta and IL-18, which had a profound impact on the study of gout flare mechanism and targeted therapy." (PMID 35844867, 2022). "However, no clinical studies are available about the effects of direct blockade of IL-18 or its receptor in gout." (PMID 31200447, 2019). "In a study among OA subjects without clinical gout, we recently demonstrated a strong positive association between synovial fluid uric level, IL18 and IL1β and OA severity as measured by imaging." (PMID 25925674, 2015). "Kim found that gout patients showed a higher expression of CXCL12 and proinflammatory cytokines, including IL-1β and IL-18, than members of the control group." (PMID 40444241, 2025). "We found that gout patients showed a higher expression of CXCL12 and proinflammatory cytokines, including IL-1β and IL-18, than members of the control group." (PMID 36979628, 2023). "We evaluated the relationship among IL-1β, IL-18, CXCL12, CXCR4, and the laboratory variables in the patients with gout." (PMID 36979628, 2023). "When the quail showed gout symptoms, the NLRP3 inflammasome was activated, and the expressions of IL-1β, TNF-α, IL-6, IL-8, and IL-18 were significantly increased." (PMID 36569836, 2022). "Similar to RA patients, the serum and synovial fluid samples of the patients with gout were detected to contain higher levels of NLRP3, caspase-1, IL-1β, and IL-18." (PMID 35629398, 2022).
gout (continued). "Acute gout flare is induced by NLRP3 inflammasome activation and the consequent conversion of pro-IL-1β and pro-IL-18 into the active forms of IL-1β and IL-18." (PMID 36430392, 2022). "The ACP inflammatory cytokine profile was similar to that seen in gout, specifically regarding the high levels of IL1B, IL6 and IL18." (PMID 29541918, 2018). "Dapansutrile may regulate extracellular matrix degradation by reducing MMP3 expression through IL6, IL18, and IL17A in the treatment of gouty arthritis." (PMID 36105284, 2022). "Considering the important effect of pro-inflammatory cytokines on the development of acute gouty arthritis, we explored whether GPS could inhibit the release of IL-1β, IL-6, IL-18, and TNF-α." (PMID 34586567, 2022). "Dapansutrile may reduce the expression of MMP3 by regulating IL6, IL18, and IL17A, thereby degrading the extracellular matrix to deal with gouty arthritis." (PMID 36105284, 2022). "The IL-1 signaling member IL-18 and its receptor IL-18R1 and the IL-6 family of cytokines members IL-6, LIF-R, and OSM were also elevated in AH, which is in line with major studies implicating IL-1-driven inflammation and IL-6 signaling in the pathogenesis of gout." (PMID 37810213, 2023). "Therefore, Dapansutrile may decrease the expression of MMP3 by regulating IL6, IL18, and IL17A, thereby degrading the extracellular matrix for the treatment of gouty arthritis." (PMID 36105284, 2022). "Finally, dapansutrile may reduce the expression of MMP3 by regulating IL6, IL18, and IL17A, thereby degrading the extracellular matrix to treat gouty arthritis." (PMID 36105284, 2022). "However, IL-18 does not appear to be directly involved in the genesis of the joint inflammatory process in gout as it is in other inflammasome-mediated diseases, such as adult Still’s disease, where IL-18 is as involved as IL-1 in determining the clinical manifestations." (PMID 40710524, 2025).